TSPAN8 (tetraspanin 8)
Diseases named in the same sentence as TSPAN8 in open-access papers (continued):
Sharing a sentence is not in itself a finding about the gene and the disease.
melanoma (continued). "We previously demonstrated that Tspan8, a member of the tetraspanin family known to exert pro-invasive functions in numerous carcinomas, is sufficient to confer invasive properties to non-invasive melanoma cells and could predict metastatic risk and patient outcomes in cutaneous melanoma." (PMID 38398085, 2024). "We previously demonstrated that Tspan8 is a transmembrane protein sufficient to confer invasiveness to non-invasive melanoma cells both in 2D cultured cells and 3D skin reconstructed models." (PMID 38398085, 2024). "We also found that ZEB1’s effect on the biomechanical properties of melanoma cells was dependent on Tspan8’s function, since the significant stiffness decrease induced by ZEB1 overexpression was abolished upon Tspan8 knockdown." (PMID 38398085, 2024). "We also found a positive correlation in three out of five ZEB1int melanomas, where ZEB1-positive areas were tightly associated with high corresponding Tspan8 expression areas." (PMID 38398085, 2024). "Overall, our results suggest that the regulation of Tspan8 expression by EMT-TF expression switching is a crucial conserved mechanism for melanoma progression." (PMID 38398085, 2024). "In particular, LCMR1 (lung cancer metastasis-related protein 1) enhanced TSPAN8 expression and promoted the invasion of melanoma cells." (PMID 38275818, 2024). "TSPAN8+ melanoma cells have elevated active MMP-3 and low TIMP-1 levels to promote keratinocyte-originated proMMP-9 activation process, collagen IV degradation and dermal colonization." (PMID 36941633, 2023). "TSPAN8 stabilizes β-catenin, which in turn directly triggers the transcription of TSPAN8, leading to melanoma invasion." (PMID 36941633, 2023). "MED19 transcription can activate the expression of endogenous Tspan8, and regulate the adhesion and invasion of melanoma in a Tspan8-dependent manner." (PMID 35047403, 2021). "In contrast, β-catenin triggers the direct transcriptional activation of TSPAN8 expression, leading to melanoma invasion." (PMID 32138170, 2020). "Keratinocytes and Tspan8+ melanoma cells were either cultured alone on de-epidermized dermis (DED) (I and II cultures, respectively) or cocultured, without or with cell–cell contacts (III and IV cultures, respectively)." (PMID 32455575, 2020). "We observed high levels of proteolytically active MMP-9 concurrently with very low levels of melanoma-derived TIMP-1 at the time of collagen IV dissolution, exclusively when melanoma cells were integrated into SR and expressed Tspan8." (PMID 32455575, 2020). "Tspan8 is undetectable at both mRNA and protein in healthy skin, but its expression is acquired by aggressive primary melanomas and lymph node metastases." (PMID 32455575, 2020). "Concordantly, that property observed in SR containing Tspan8+ melanoma cells was abrogated when Tspan8 expression was silenced." (PMID 32455575, 2020). "This indicates that Tspan8+ melanoma cells, once invading the dermis, acquire the capability of expressing the precursor forms of MMP-9 and MMP-3, which were previously provided by the keratinocytes when situated in the epidermis." (PMID 32455575, 2020). "Conversely, Tspan8 depletion in invasive cells strongly inhibited matrigel invasion and efficiently prevented melanoma cells from crossing the DEJ, concurrently to a drastic decrease in proMMP-9 activation." (PMID 32455575, 2020). "Our data, together with the data available in the literature, reveal that Tspan8 expression in melanoma cells promotes the activation of keratinocyte-generated proMMP-3 in the stroma, which engages MMP-9 activation and DEJ proteolysis." (PMID 32455575, 2020).
melanoma (continued). "Accordingly, a Tspan8-specific antibody efficiently targeting in vivo Tspan8+ melanoma xenografts was able to reduce MMP-9 activity, DEJ breakdown, and dermal invasion." (PMID 32455575, 2020). "We observed that non-invasive melanoma cells gained strong invasive properties after the ectopic expression of Tspan8 in matrigel and SR concomitantly to the production of high levels of active MMP-9." (PMID 32455575, 2020). "We were the first to reveal that Tspan8 expression is sufficient to transform non-invasive melanoma cells into invasive cells." (PMID 32455575, 2020). "Mechanistically, Tspan8+ melanoma cells cooperate with surrounding keratinocytes within the epidermis to promote keratinocyte-originated proMMP-9 activation process, collagen IV degradation and dermal colonization." (PMID 32455575, 2020). "MMP-9 and MMP-3 were mainly expressed by keratinocytes whereas TIMP-1 was mainly expressed by Tspan8+ melanoma cells." (PMID 32455575, 2020). "Overall, our results indicate that interaction between Tspan8+ melanoma cells and neighboring keratinocytes are essential to drive MMP-9 activation, collagen IV dissolution, and subsequent dermal invasion." (PMID 32455575, 2020). "We found that mere Tspan8 gain of expression is sufficient to promote melanoma invasive behavior and acts by driving proMMP-9 activation leading to DEJ proteolysis." (PMID 32455575, 2020). "Our work provides strong evidence of the primary involvement of Tspan8 in melanoma–keratinocyte crosstalk leading to efficient DEJ degradation." (PMID 32455575, 2020). "Overall, these data show that, by itself, Tspan8 expression was sufficient to trigger proMMP-9 activation process and collagen IV dissolution, allowing melanoma cells to cross DEJ and invade dermis." (PMID 32455575, 2020). "Here, we investigated Tspan8 mechanisms of action during dermal invasion, using a validated skin-reconstruct-model that recapitulates melanoma dermal penetration through an authentic DEJ." (PMID 32455575, 2020). "TSPAN8 is upregulated at the mRNA and protein levels in melanoma cells, where its levels are correlated with an invasive phenotype." (PMID 32138170, 2020). "First, we showed that it allows efficient selective in vivo imaging of Tspan8+ human melanoma xenografts, demonstrating its high target specificity." (PMID 32455575, 2020). "This work also displays solid arguments for the use of Tspan8-blocking antibodies to impede early melanoma spreading and therefore metastasis." (PMID 32455575, 2020). "Tspan8 exhibits a functional role in many cancer types including pancreatic, colorectal, oesophagus carcinoma, and melanoma." (PMID 30982971, 2019). "Tspan8 was originally identified as a tumor-associated antigen by an antibody (CO-029), CD63 by a melanoma-associated antigen (ME491), CD151 was re-identified by an antimetastatic antibody, and CD82/KAI1 as a metastasis suppressor gene." (PMID 29946318, 2018). "Tspan8 was also shown to modulate invasion of melanoma in vitro and in vivo through a β1 integrin by affecting integrin-linked kinase signaling and its downstream target AKT." (PMID 29946318, 2018). "We then evaluated the clinical relevance of these results by analyzing P-ILK expression in human primary melanomas (n= 21) and benign nevi (n=13), previously selected and shown to strongly or faintly express Tspan8, respectively." (PMID 28188308, 2017). "We previously identified tetraspanin 8 (TSPAN8) as an important modulator of melanoma invasiveness, and several of its transcriptional regulators, which affect TSPAN8 expression during melanoma progression toward an invasive stage." (PMID 28368391, 2017).
melanoma (continued). "Accordingly, Tspan8 is undetectable in healthy skin and exclusively expressed in primary melanomas and lymph node metastases." (PMID 28188308, 2017). "Overall, Tspan8 expression attenuates melanoma cell-matrix anchorage by modulating β1-ligand binding, mainly through integrin avidity." (PMID 28188308, 2017). "These in vitro findings have in vivo significance, since we found that the expression of Tspan8 is inversely correlated with ILK phosphorylation in melanoma xenografts and in human melanocytic lesions." (PMID 28188308, 2017). "Altogether, the in vitro, in vivo and in situ data highlight a novel regulatory role for Tspan8 in melanoma progression by modulating cell-matrix interactions through β1 integrin-ILK axis and establish Tspan8 as a negative regulator of ILK activity." (PMID 28188308, 2017). "This is consistent with the fact that Tspan8 formed an immunoprecipitable complex with β1 integrins at the surface of invasive melanoma cells and reduced adhesion to a wide range of ligands." (PMID 28188308, 2017). "To understand how Tspan8 expression is turned on, inducing invasive properties in melanoma cells, we recently performed an RNA interference-based screen, for several genes known to regulate the metastatic process." (PMID 28368391, 2017). "Tspan8 expression in invasive melanoma cells was responsible for inhibition of ILK phosphorylation and its downstream target Akt-S473, concomitantly with reduced adhesiveness." (PMID 28188308, 2017). "In cutaneous melanoma, we previously showed that Tspan8 expression is undetectable in normal skin and becomes expressed at very high levels in primary melanomas and lymph node metastases." (PMID 28368391, 2017). "Melanoma cells were surface stained for TSPAN8, RELN and FXYD5 or intracellularly stained for renalase, CAPG, BCL11A and ID3." (PMID 21081927, 2011). "Altogether, these results indicate that TSPAN8 has a role in the invasive behaviour of melanoma cells." (PMID 21081927, 2011). "We next sought to determine the role and significance of endogenous TSPAN8 silencing on melanoma cell viability and proliferation." (PMID 21081927, 2011). "No significant impairment in wound closure was detected between melanoma cells transfected with TSPAN8-specific or scramble siRNAs in the presence of either type of collagen, as well as on matrigel (data not shown)." (PMID 21081927, 2011). "In contrast, melanoma cells stained strongly positive for TSPAN8 in primary melanomas and in lymph nodes: immunoreactivity was observed in 8 of the 13 RGP lesions, in 10 of the 35 VGP lesions and in 2 of the 6 lymph node metastases." (PMID 21081927, 2011). "Here, we found a higher frequency of TSPAN8 expression in early (RGP) than later stages of melanoma progression (VGP, metastatic)." (PMID 21081927, 2011). "In conclusion, the present findings highlight several new aspects of the role of TSPAN8 in the initial steps of human melanoma progression." (PMID 21081927, 2011). "An interesting finding in this study is that siRNA TSPAN8 knockdown reduced the invasive outgrowth of melanoma spheroids embedded in matrigel." (PMID 21081927, 2011). "TSPAN8, a member of the tetraspanin family, was thereby identified, confirmed as exclusively expressed by melanoma cells from a panel of invasive cell lines and functionally characterized as a novel mediator of cutaneous melanoma invasion." (PMID 21081927, 2011). "Elevated TSPAN8 mRNA expression has been reported in several cancer types, including colorectal, pancreatic, gastric, and hepatocellular carcinomas, as well as in melanoma and glioma." (PMID 40428124, 2025). "Worth mentioning, tetraspanin 8 plays a role in melanoma that goes beyond intracellular functions." (PMID 39031113, 2024).
melanoma (continued). "In order to determine whether Tspan8 could be a major downstream effector of the EMT-TF expression switch for biomechanical adaptation in melanoma cells, we first analyzed whether the modulation of Tspan8 expression could affect melanoma cell stiffness." (PMID 38398085, 2024). "This study allowed us to propose that cell stiffness could be a biomarker of melanoma progression in vitro, in vivo, and potentially in patients, linked to EMT-TF phenotype switching and Tspan8 expression regulation." (PMID 38398085, 2024). "Similarly, TSPAN8 expression was reported to stabilize β-catenin, which in turn enhanced TSPAN8 transcription in melanoma cells." (PMID 38275818, 2024). "We previously identified Tspan8 as a key actor in melanoma invasiveness." (PMID 32455575, 2020). "In summary, these findings suggest that TSPAN8 is a promising therapeutic target for radioimmunotherapy in a broad range of TSPAN8-expressing cancers, including melanoma, glioma, hepatocellular carcinoma, ovarian and gastric cancers as well as aggressive CRC tumors." (PMID 32138170, 2020). "Furthermore, an anti-Tspan8 monoclonal antibody specifically targeting Tspan8+ melanoma xenografts in vivo significantly reduces dermal invasion by strongly impairing proMMP-9 activation process and collagen IV breakdown." (PMID 32455575, 2020). "Importantly, MMP-3 full activation is Tspan8-dependent as SR generated with non-invasive melanoma cells ectopically expressing Tspan8 acquired the property to produce a large amount of fully active MMP-3." (PMID 32455575, 2020). "Our data reveal that Tspan8 drives mutual cooperation between melanoma cells and epidermal microenvironment to trigger the proMMP-9 activation process primarily produced by the keratinocytes, leading to collagen IV-containing DEJ proteolysis and dermal invasion." (PMID 32455575, 2020). "We next examined whether a blocking monoclonal anti-Tspan8 antibody, previously shown to be effective in delaying the growth of human colon xenografts, could influence melanoma invasion." (PMID 32455575, 2020). "We demonstrate that Tspan8 is sufficient to induce melanoma cells’ translocation to the dermis." (PMID 32455575, 2020). "Here, we address how Tspan8 participates in the dermal–epidermal junction (DEJ) proteolysis during melanoma invasion and whether it contributes to tumor–keratinocyte crosstalk." (PMID 32455575, 2020). "We thus wondered whether active MMP-9, exclusively observed when Tspan8+ melanoma cells were surrounded by keratinocytes, coincided with low levels of TIMP-1." (PMID 32455575, 2020). "Using silencing and ectopic expression strategies, we showed that Tspan8-mediated invasion of melanoma cells resulted from defects in cell-matrix anchorage by interacting with β1 integrins and by interfering with their clustering, without affecting their surface or global expression levels." (PMID 28188308, 2017). "Indeed, Tspan8 impairs integrin-mediated anchorage of melanoma cells to matrix components by negatively regulating ILK activity, leading to the inhibition of its downstream target Akt-S473 and β1 integrin clustering." (PMID 28188308, 2017). "The Tspan8-mediated effect was not limited to a specific type of matrix protein and the β1 integrin subunit, common to both fibronectin and collagen receptors, was predominantly expressed in melanoma cells." (PMID 28188308, 2017). "To investigate whether Tspan8 could be part of a β1 integrin complex that might influence cell-matrix anchorage, we immunoprecipitated Tspan8 from invasive melanoma cells after surface biotinylation." (PMID 28188308, 2017).
melanoma (continued). "To determine whether the Tspan8-mediated invasion of melanoma cells may result from a defect in cell-matrix anchorage, we knocked-down Tspan8 expression in invasive cells by the previously validated SMART pool siRNA." (PMID 28188308, 2017). "The correlation between TSPAN8 expression and the invasive phenotype led us to examine whether this protein was critical to the migratory behaviour of melanoma cells." (PMID 21081927, 2011). "The study spotlighted TSPAN8, a member of the tetraspanin family, showing it to be strongly expressed, at both mRNA and protein levels, by invasive melanoma cells as compared with normal melanocytes or non-invasive melanoma cells." (PMID 21081927, 2011). "Given that the migratory/invasive behaviour of melanoma cells cultured in a 3D environment required a Rho GTPase protein, further studies will be needed to investigate whether TSPAN8-mediated invasion is dependent on Rho signalling." (PMID 21081927, 2011). "TSPAN8 expression may enable melanoma cells to cross the cutaneous basement membrane, leading to dermal invasion and progression to metastasis." (PMID 21081927, 2011). "Moreover, ZEB1 expression correlated with Tspan8 expression in patient melanoma lesions." (PMID 38398085, 2024). "In addition, the exosomal form of tetraspanin 8 may contribute to the invasiveness of melanoma cells." (PMID 39031113, 2024). "We found on both the whole HSR and HSR sections that Tspan8’s ectopic expression was sufficient to decrease melanoma cell stiffness, whereas Tspan8’s inhibition increased it, confirming that Tspan8 expression could enhance melanoma dermal invasion by reducing melanoma cell stiffness." (PMID 38398085, 2024). "We identified a positive correlation between ZEB1 and the Tspan8 expression level since ZEB1high melanomas were mainly associated with high expression levels of Tspan8 (five out of seven), contrary to ZEB1low melanomas, which showed low to no Tspan8 expression." (PMID 38398085, 2024). "Ectopic Tspan8 expression in non-invasive cells significantly increased tumor growth and weight whereas knockdown of endogenous Tspan8 in invasive cells drastically inhibited tumor occurence and growth, further demonstrating the pro-oncogenic function of Tspan8 in melanoma." (PMID 28188308, 2017). "Hence TSPAN8 was suggested a promising target in early detection, at least in melanoma." (PMID 26993598, 2016). "If the present in vitro findings have any physiological relevance, it is thus conceivable that TSPAN8 expression might give melanoma cells the ability to cross the cutaneous basement membrane, an early event leading to dermal invasion and progression to metastatic disease." (PMID 21081927, 2011). "TSPAN8 could be a promising target in early detection and treatment of melanoma." (PMID 21081927, 2011). "We found that ectopic Tspan8 expression or the enrichment of Tspan8 expression by FACS sorting strongly reduced melanoma cell stiffness, whereas Tspan8’s stable inhibition by shRNA increased their stiffness." (PMID 38398085, 2024). "Our data are the first to establish Tspan8 as a negative regulator of ILK activity, thus inhibiting β1 integrin-mediated anchorage to matrix required for allowing melanoma invasion." (PMID 28188308, 2017). "Since aggressive melanoma cells acquire the ability to invade surrounding tissues by changing their interactions with the local environment, the present study investigated whether Tspan8 may influence cell-matrix interactions and regulate downstream targets, leading to an aggressive behaviour." (PMID 28188308, 2017). "We then investigated the expression of TSPAN8 and CAPG protein on another seven melanoma cell lines/clones, in addition to the two clones, to find any correlation with the invasive potential of melanoma cells." (PMID 21081927, 2011).